Y_RNA (Y RNA )
Gene: Miscellaneous RNA gene on chromosome 12 (112,149,360 to 112,149,472, forward strand). Ensembl gene ENSG00000200135.
Homologues: Orthologues: chimpanzee Y_RNA (98% identical), macaque Y_RNA (90% identical), guinea pig Y_RNA (73% identical). Paralogues in human: RNY1 (90% identical), Y_RNA (89% identical), Y_RNA (88% identical), Y_RNA (87% identical), RNY1P11 (86% identical), Y_RNA (86% identical), Y_RNA (85% identical), RNY1P15 (84% identical), Y_RNA (84% identical), RNY1P8 (83% identical), Y_RNA (83% identical), RNY1P10 (82% identical), and 98 more.